CD34 (CD34 molecule)
Diseases named in the same sentence as CD34 in open-access papers (continued):
Sharing a sentence is not in itself a finding about the gene and the disease.
HCMV infection (continued). "Early studies using in vitro systems indicated that HCMV infection of CD34+ hematopoietic progenitor cells (HPCs) alters myeloid development." (PMID 32268565, 2020). "We recently published that latent HCMV infection of CD34+ HPCs induces the secretion of TGF-β that is responsible for virus-mediated myelosuppression." (PMID 32268565, 2020). "Cytomegalovirus infection was the most common viral infection observed in both groups, whereas adenovirus haemorrhage cystitis was only found in the CD34-selected group." (PMID 30670057, 2019). "Toxicity and viral infections, such as cytomegalovirus infection and herpes zoster, were more frequently found in the CD34-selected group than in the unmanipulated group." (PMID 30670057, 2019). "Our model takes a simplified approach for studying HCMV infections in vivo model using NRG female mice transplanted with CB purified CD34+ cells." (PMID 30524448, 2018). "Further, in HCMV infection UL7 is required for HCMV reactivation from latency in both in vitro CD34+ cells and in vivo humanized mice as well as G-CSF-induced myelopoiesis in humanized mice." (PMID 30127257, 2018). "Early studies using in vitro CD34+ HPC systems indicated that HCMV infection of CD34+ HPCs alters lymphoid and myeloid development." (PMID 29691342, 2018). "We next examined viral gene expression in experimentally infected CD34+ HPCs, which are another well-characterized site of latent HCMV infection." (PMID 29535194, 2018). "During latent HCMV infection, virus is known to reside in CD34+ hematopoietic stem cells and derivative CD14+ monocytes." (PMID 28694811, 2017). "In support of this possibility, CD34+ progenitors harbouring a latent HCMV infection exhibit an increased resistance to apoptosis." (PMID 28869497, 2017). "In the present study, we established an experimental HCMV latency model with the HCMV clinical strain NR-1 in Kasumi-3 cells and CD34+ primary hematopoietic progenitor cells (HPCs) and then monitored HCMV-encoded miRNAs at various stages of HCMV infection." (PMID 27824944, 2016). "In conclusion, our data suggest that latent HCMV infection of CD34+ cells results in changes in the levels of anti-apoptotic cellular factor PEA-15, which are mediated via cIL-10 to enhance cell survival." (PMID 25957098, 2015). "Finally, while technology to knock down or manipulate host gene expression or overexpress a transgene in CD34+ cells exists, this remains a significant challenge in the context of HCMV infection." (PMID 40736257, 2025). "In this study, we investigated whether latent HCMV infection modulates the STING/p-TBK1/p-IRF3 pathway to influence CD34+ cell differentiation." (PMID 40872823, 2025). "However, the influence on the expression of type I IFNs and its impact on CD34+ HSPCs differentiation during latent HCMV infection are poorly understood." (PMID 40872823, 2025). "Type I interferons (IFNs) are known to induce differentiation of CD34+ cells during infection, but whether this process is modulated during latent HCMV infection remains unclear." (PMID 40872823, 2025). "Furthermore, huNSG mice represent the only animal model capable of supporting HCMV infection and we have shown that huNSG mice engrafted with human CD34+ HPCs to be a reliable and robust model of both latent and lytic infection." (PMID 37782657, 2023). "Finally, we observed that UL7, miR-US5-1, and miR-UL112-3p are expressed in the early stages of HCMV infection in CD34+ HPCs and act to reduce FOXO3a activity to promote survival of infected hematopoietic progenitor cells." (PMID 33408225, 2021). "Latent HCMV infection has already been shown to downregulate APOBEC3G in CD34+ progenitor cells." (PMID 33679688, 2020). "Interestingly, CMV infection of CD34+ HPCs results in a transient increase in surface expression of EGFR early on in infection." (PMID 30127257, 2018).
HCMV infection (continued). "It has been hypothesized that human cytomegalovirus (HCMV) infection, especially in monocyte and CD34 (+) myeloid cells, acts as a important regulator of immune system to promote inflammation in multiple autoimmune diseases." (PMID 29367719, 2018). "Further studies of HCMV infection in CD34 cells will help in defining whether CD34+ infected cells undergo cell differentiation by increased expression of other markers such as CD33, CD38, HLA-DR or cytokines." (PMID 15673469, 2005). "The cell surface receptor CD34 is detected on a wide range of different progenitor cell types, and the importance of cell sorting in latency assays is further underscored by the finding that HCMV infection of different subpopulations of CD34+ HPCs results in different functional outcomes." (PMID 35012351, 2022). "However, there are differences between subpopulations of progenitor cells: CD34+/CD38− cells support an HCMV infection with the hallmarks of latency, but a subset of CD34+/CD38− cells expressing a stem cell phenotype (lineage−/Thy-1+) support productive HCMV infection." (PMID 32296651, 2020). "In this model, CD34+ HPCs are engrafted into NOD-scidIL2Rγc null mice (huNSG), followed by HCMV infection." (PMID 29691342, 2018). "The changes in EGFR signaling in CD34+ HPCs may explain some of the infection-induced alterations in myeloid differentiation, as levels of the inflammatory cytokine interleukin-12 are increased during CMV infection and further exacerbated by inhibition of EGFR signaling." (PMID 30127257, 2018). "In terms of adverse events, there were multiple cases of viral infections such as cytomegalovirus infection and herpes zoster in the CD34-selected group, probably due to the absence of lymphocytes just after the auto-HSCT." (PMID 30670057, 2019). "To address this challenge, we examined HCMV infection by comprehensive analysis of RNA-seq data from diverse human tissues and further used scRNA-seq to analyze gene expression of latently infected CD14+ monocytes and CD34+ HPCs." (PMID 29535194, 2018). "Together with our findings that treatment of latently HCMV infected CD34+ HPCs at the time of reactivation with DKK1 decreases the ability of the virus to reactivate in vitro, this suggests a conserved role of the Wnt pathway in CMV infection that is different from α- and γ-herpesvirus." (PMID 37772824, 2023). "The latency model established in THP-1 cells may be restricted to mimicking quiescent HCMV infection in the host, and more investigations in other experimental HCMV latency models, such as Kasumi-3 cells and CD34+ primary HPCs, as well as clinical samples are needed." (PMID 33746965, 2021). "Foremost among the advantages of the vector system we have described is the potential ability to efficiently infect and deliver genetic information to hematopoietic stem cells (CD34+) and other dividing and non-dividing cell types which may support HCMV infection." (PMID 15673469, 2005).
ischemia (34 papers, 2010 to 2025). A hypoperfusion of the BLOOD through an organ or tissue caused by a PATHOLOGIC CONSTRICTION or obstruction of its BLOOD VESSELS, or an absence of BLOOD CIRCULATION. "Exogenous Ang2 induces angiogenesis by upregulating CD34 expression in cultured ECs in vitro and extending the CD34-positive vascular area and length during the acute phase of ischemia." (PMID 39769300, 2024). "Cord blood has been successfully used to stimulate angiogenesis in various models of ischemia, with the CD34+ fraction of cord blood possessing the ability to differentiate into endothelial cells." (PMID 39061976, 2024). "After bench-top experiments, athymic mouse and rabbit models of hindlimb ischemia were given human CD34+ cells." (PMID 36660500, 2022). "Currently, a phase 3 trial using CD34+ stem cells for critical limb ischemia due to atherosclerosis and Buerger’s disease is near completion in Japan." (PMID 34066713, 2021). "Following bench-top studies, human CD34+ cells were administered into athymic mouse and rabbit models of hindlimb ischemia." (PMID 34066713, 2021). "Over the following years, several studies established that CD34+ cells significantly augmented perfusion in hindlimb ischemia models." (PMID 34066713, 2021). "Growing evidence from clinical trials has demonstrated the safety and effectiveness of autologous CD34+ cell therapy for treating ischemia-related left ventricular (LV) dysfunction." (PMID 32272750, 2020). "Based on these findings, we consider that both the seeded CD34+ cells and aortic scaffold contribute to the neovascular formation in the hind-limb ischemia model of nude mice." (PMID 32104703, 2020). "Hindlimb ischemia mice received eGFP mouse bone marrow cells, and the levels of CD34+/eGFP+ cells were determined to investigate the effects of atorvastatin or rosuvastatin on EPC mobilization." (PMID 26309120, 2015). "After hindlimb ischemia surgery, the populations of endogenous EPCs (defined as CD34+/Flk-1+ cells) were quantified by flow cytometry." (PMID 26309120, 2015). "The expressions of CD34 in heart was significantly increased in vehicle-treated complex model compared to that from the normal control, presumably as a result of ischemia-induced angiogenic response." (PMID 24903055, 2014). "When delivered intra-arterially into the ischemic hindlimbs of ApoE−/− mice, CD34+/M-cad+ BMCs alleviated ischemia and significantly improved blood flow compared with CD34+/M-cad− BMCs, CD34−/M-cad+ BMCs, or unselected BMCs." (PMID 21677770, 2011). "CD34+/M-cad+ BMCs represent a new progenitor cell type that effectively alleviates hindlimb ischemia in ApoE−/− mice by consistently improving blood flow and promoting arteriogenesis." (PMID 21677770, 2011). "Our finding that the number of CD34+ cells is inversely proportional to claudication distance indirectly indicates that ischaemia induced through interval training could increase the number of CD34+ cells." (PMID 37895025, 2023). "CD34 was restrictively expressed in a mesenchymal cell and EC populations despite some cell-cluster variations between species, which was validated and also found to be enhanced in ischemia through immunostaining on cardiac tissue sections." (PMID 37147443, 2023). "The results showed that CD34 expression on the ipsilateral side of ischemia increased significantly relative to the contralateral ischemia, and immunohistochemistry and immunofluorescence staining further verified that CD34 expression increased in blood vessels after ischemic injury." (PMID 36358355, 2022). "Consistently, our phase I clinical trial has also shown that intracoronary (IC) administration of autologous CD34+ cells significantly improved not only short-term but also long-term ischemia-related LV dysfunction as well as symptoms of angina and heart failure (HF)." (PMID 32272750, 2020).
ischemia (continued). "The results showed that CD34 and α-SMA expressions were associated with a significant increase in the model group compared with sham rats, this increase was most likely caused by local ischemia stimulation." (PMID 31938036, 2020). "The data from preclinical studies suggest that CD34+ cells differentiate into endothelial cells, integrate into the vasculature, and secrete angiogenic factors, promoting vessel regeneration in the microcirculation and improving myocardial perfusion in ischemia-induced tissue injury." (PMID 39859963, 2024). "Taken together, records from preclinical studies propose that CD34+ cells differentiate into ECs, integrate into vascular system, and secrete angiogenic factors, promoting vascular regeneration in the microcirculation and improving myocardial perfusion in ischemia-induced tissue damage." (PMID 37138792, 2023). "Our results reveled that hindlimb ischemia surgery may have induced more intense CXCR4 expression on circulating CD34+/Flk-1+ EPCs; treatment with either atorvastatin or rosuvastatin may have significantly up-regulated the relative intensity of CXCR4 expression on CD34+/Flk-1+ EPCs." (PMID 26309120, 2015). "Asahara reported that EPCs express CD34 and Flk-1 and that EPC transplantation improves neovascularization in an ischemia model." (PMID 37953756, 2023). "The expressions of the EPC markers CD34+ and CD133+ significantly decreased in the peripheral blood in hindlimb post-ischemia." (PMID 34422926, 2021). "Thus, circulating vascular precursor cells CD34+ and endothelial progenitor cells (EPCs) have been used for tissue regeneration and angiogenesis following ischemia due to the fact that they may play a role in functional collateralization and secrete neurotrophic cytokines and proangiogenic factors." (PMID 34208272, 2021). "The feasibility and safety of intracoronary administering CD34+ cells to patients with ischemia with non-obstructive coronary arteries (INOCA) with coronary microvascular dysfunction (CMD) and persistent angina are established by this trial." (PMID 36660500, 2022). "In addition, the present mechanistic data indicate that CD34-positive BM cells produce VEGF by downregulating miR-762 and miR-3072-5p, and that VEGF protects spinal cord neurons against ischemia." (PMID 27905554, 2016). "Since CD34+/Flk1+ ESCs/EPCs increased in the circulation and pro-angiogenic factors were elevated in the brain by PTH, we tested the hypothesis that post-ischemia angiogenesis could be enhanced after chronic PTH treatment." (PMID 24503654, 2014). "The use of intramyocardial injection of autologous bone marrow derived mononuclear cells such as CD34+ and AC133+ stem cells has also yielded positive efficacy signals with regard to angina improvement and myocardial perfusion in patients with refractory ischemia." (PMID 20849586, 2010). "Non-conditioned AMI induces MMP-2 release, hampering the ischemia-induced increase in SDF-1α and CXCR4 by cleaving the SDF-1α/CXCR4 axis, with diminished mobilization of the angiogenic CD34+ cells." (PMID 28299177, 2016).
myeloproliferative neoplasm (34 papers, 2014 to 2026). A clonal hematopoietic stem cell disorder, characterized by proliferation in the bone marrow of one or more of the myeloid (i.e., granulocytic, erythroid, megakaryocytic, and mast cell) lineages. "In PMF, the mobilization of CD34 cells into peripheral blood is a hallmark feature, with their levels exceeding those in healthy individuals by over 300 times and surpassing other myeloproliferative disorders by 20–30 times." (PMID 40699626, 2025). "Primary myelofibrosis (PMF) is a clonal myeloproliferative neoplasm (MPN) characterized by progressive bone marrow (BM) fibrosis, higher numbers of circulating CD34+ progenitor cells, splenomegaly, cytopenias, and risk of leukemic transformation." (PMID 36212480, 2022). "A single point mutation of the tyrosine kinase JAK2, common in myeloproliferative cancers, results in upregulation of La/SSB in both cell culture and in CD34+ progenitor cells from patients with myeloproliferative neoplasms." (PMID 34636174, 2022). "CML is a myeloproliferative neoplasm characterized by the expansion of the early hematopoietic progenitor cells pool which express CD34 antigen." (PMID 36175852, 2022). "Regarding BCR-ABL1-positive myeloproliferative neoplasms, CD34+ cells from CML patients were targeted by IL-33." (PMID 31652497, 2019). "In this light, we performed OXR1 silencing in CD34+ cells, which are the target cells of CALR mutation and from whom the myeloproliferative disease originates." (PMID 31332222, 2019). "The PROTAC ARV-825 induces sustained apoptosis in CD34+ post-myeloproliferative neoplasms (MPN) secondary AML (sAML) cells." (PMID 31311566, 2019). "EVs released by MSCs from patients with myeloproliferative neoplasms (MPN) were found to be selectively enriched in miR155, and they induced an increase in granulocyte colony forming unit number from neoplastic CD34+." (PMID 28574430, 2017). "Myeloproliferative neoplasms (MPN) are chronic myeloid cancers thought to arise at the level of CD34+ hematopoietic stem/progenitor cells." (PMID 26468945, 2015). "Nonetheless, a multicenter study of the ELN iMDSFlow WG, published in 2023, confirmed that a percentage of ≥3% marrow myeloid progenitors (CD45weak/SSClow/CD34+/CD19) strongly suggests the existence of MDS or myelodysplastic/myeloproliferative neoplasms (MDS/MPN)." (PMID 39544295, 2024). "A marked reduction in PP2A activity was also found in CD34+ stem cells isolated from bone marrow and peripheral blood of JAK2-driven myeloproliferative neoplasms (MPN), compared with those isolated from healthy individuals." (PMID 36345878, 2022). "We also show that its expression is increased in both CD34+ circulating progenitors and in the serum of patients with JAK2-dependent myeloproliferative neoplasms with fibrosis." (PMID 29650953, 2018). "In this work, we aimed at optimizing a workflow for cell immunostaining, fixation and WGA dedicated to the single-cell genomic analysis of the hematopoietic CD34+CD38- stem compartment, in which originate hematological malignancies such as Myeloproliferative Neoplasms." (PMID 33036143, 2020). "We chose the MN1 oncogene to enhance the engraftment of CMML cells as MN1 enhances self-renewal and blocks differentiation of CD34+ cord blood cells in vitro and induces a myeloproliferative disease, but not AML, in vivo." (PMID 32576961, 2020). "The first bioreactor system was recently developed to maintain malignant CD34+ cells from AML and myeloproliferative neoplasm (MPN) patients for up to 3 weeks." (PMID 35406494, 2022). "Furthermore, the ROCK inhibitor, Fasudil, has been shown to decrease disease burden in myeloproliferative disease (MPD) mouse models and combination of imatinib with either Fasudil or the ROCK inhibitor Y-27632 showed synergistic inhibition of CD34+ chronic myeloid progenitor cell growth." (PMID 35365653, 2022).
myeloproliferative neoplasm (continued). "Primary myelofibrosis (PMF) is a Philadelphia-negative (Ph−) myeloproliferative disorder, showing abnormal CD34+ progenitor cell trafficking, splenomegaly, marrow fibrosis leading to extensive extramedullary haematopoiesis, and abnormal neoangiogenesis in either the bone marrow or the spleen." (PMID 27281335, 2016). "In addition, GAS2 silencing did not disturb the growth of normal CD3+ or CD34+ cells, which supports GAS2 as a suitable therapeutic target to eradicate T‐ALL cells or other hematological malignancies with aberrant GAS2 expression, such as CML and myeloproliferative neoplasm." (PMID 36054080, 2022).